RNU7-123P (RNA, U7 small nuclear 123 pseudogene)
Gene: Small nuclear RNA gene on chromosome 1 (63,536,711 to 63,536,770, reverse strand). Ensembl gene ENSG00000251720.
Homologues: Orthologues: macaque U7 (95% identical). Paralogues in human: RNU7-37P (88% identical), RNU7-40P (87% identical), RNU7-120P (85% identical), RNU7-35P (85% identical), RNU7-48P (85% identical), RNU7-70P (85% identical), RNU7-97P (85% identical), RNU7-111P (83% identical), RNU7-130P (83% identical), RNU7-14P (83% identical), RNU7-18P (83% identical), RNU7-20P (83% identical), and 142 more.